G3BP1 (G3BP stress granule assembly factor 1)
Diseases named in the same sentence as G3BP1 in open-access papers (continued):
Sharing a sentence is not in itself a finding about the gene and the disease.
glioma (1 paper, 2025). A benign or malignant brain and spinal cord tumor that arises from glial cells (astrocytes, oligodendrocytes, ependymal cells). "Further IHC staining of a glioma tissue microarray revealed that a high proportion of nuclear G3BP1 was associated with poor prognosis." (PMID 40858563, 2025). "Moreover, the inhibition of AEP promoted the tumor-suppressing effect of chemotherapeutic drugs, whereas AEP-cleaved G3BP1 rescue reversed the effect in both OS and glioma models." (PMID 40858563, 2025). "Relative to those in normal- or low-grade glioma tissues, high levels of AEP and G3BP1 truncations were found in high glioma tissues and OS tumor tissues." (PMID 40858563, 2025).
head and neck squamous cell carcinoma (1 paper, 2024). A squamous cell carcinoma that arises from any of the following anatomic sites: lip and oral cavity, nasal cavity, paranasal sinuses, pharynx, larynx, and salivary glands. "In this study, we searched for differential expression of G3BP1 mRNA in malignant tumors and their corresponding unpaired tissues or paired tissues, including (Head and Neck Squamous Cell Carcinoma, HNSCC)." (PMID 38164170, 2024).
human papillomavirus infection (1 paper, 2024). "The functions of stress-induced G3BP1 targets (T60_only) were enriched to Kyoto Encyclopedia of Genes and Genomes (KEGG) pathways of protein processing in the endoplasmic reticulum and human papillomavirus infection, consistent with previous observations." (PMID 38200227, 2024).
insulinoma (1 paper, 2025). "We show in mouse insulinoma MIN6-K8 cells exposed to fasting glucose levels that G3BP1 and its paralog G3BP2 colocalize to cytosolic condensates with eIF3b, phospho-AMPKαThr172 and Ins1/2 mRNA." (PMID 40355555, 2025). "Based on this literature and our findings, there seems to be a connection in insulinoma MIN6-K8 cells between low glucose, AMPKα-phosphorylation/activation, and presence of G3BP1+ condensates, via the aldolase-phospho-AMPKαThr172-G3BP1 axis." (PMID 40355555, 2025). "Our studies began by analyzing the expression of G3BP1 and its paralogue G3BP2 in glucose-responsive mouse insulinoma MIN6-K8 cells." (PMID 40355555, 2025).
iron deficiency (1 paper, 2024). "To address whether iron limitation promotes the formation of SGs, we determined the subcellular localization of two SG-specific components during iron deficiency, G3BP1 and PABP1, by immunofluorescence using specific antibodies." (PMID 38605136, 2024).
leukemia (1 paper, 2023). A malignant (clonal) hematologic disorder, involving hematopoietic stem cells and characterized by the presence of primitive or atypical myeloid or lymphoid cells in the bone marrow and the blood. "Similar to other leukemia-associated CSF1R fusions, G3BP1::CSF1R retains an amino-terminal dimerization domain termed nuclear transport factor 2-like (NTF2L) from the partner fused to the tyrosine kinase domain of CSF1R." (PMID 37002311, 2023).
liver failure (1 paper, 2025). A liver disease characterized by the liver losing or has lost all of its function. "Using Cox regression and random forest modeling, they found that elevated G3BP1 expression was positively correlated with improved prognosis in liver failure patients." (PMID 41425091, 2025).
malignant glioma (1 paper, 2025). A grade III or grade IV glioma arising from the central nervous system. "This study revealed that chemotherapeutic drugs activated the cysteine protease asparagine endopeptidase (AEP) to specifically cleave the SG core protein G3BP1 at N258/N309 in OS and malignant glioma." (PMID 40858563, 2025). "High levels of AEP and G3BP1 truncations in cancerous tissues are potential factors for malignancy and poor prognosis in OS and malignant glioma." (PMID 40858563, 2025). "In this study, chemotherapeutic drug-activated AEP specifically cleaved G3BP1 at N258/N309, producing tG3BP1-Ns, which modulated SG dynamics; moreover, tG3BP1-Cs sequestered mRNAs of ribosomal proteins in the nucleolus to repress translation in OS as well as malignant glioma." (PMID 40858563, 2025).
myeloid neoplasm (1 paper, 2017). Proliferation of myeloid cells originating from a primitive stem cell. "In summary, comprehensive molecular analyses using SNP-A karyotyping, WES and targeted sequencing revealed recurrent somatic mutations involving CSNK1A1 and G3BP1 in the CDR and DDX41 in the CRR in myeloid neoplasms with the del(5q)." (PMID 28031539, 2017).
neuroendocrine prostate tumors (1 paper, 2025). "Using DuNE cells to model therapy-induced neuroendocrine prostate tumors, we observed that Lin28b specifically localizes to SGs, as evidenced by its co-localization with SG markers G3BP1 and YB-1, but not with DCP1, a P-body biomarker, under stress conditions." (PMID 39800739, 2025).
oral cancer (1 paper, 2022). "In the current study, we identified that G3BP1 can facilitate adaptive reactions of macrophages in response to adverse conditions in the tumor microenvironment, and these effects of G3BP1 simultaneously stimulated the expression of CCL13 from M2 TAMs, consequently improving oral cancer metastasis." (PMID 36291863, 2022).
Pca (1 paper, 2021). "Overall, our findings confirm that G3BP1 is abundantly expressed in aggressive PCa samples and strongly associated with the accumulation of SPOP substrates AR and TRIM24." (PMID 34795264, 2021). "Transcriptomic analysis and functional studies reveal a G3BP1-SPOP ubiquitin signaling axis that promotes PCa progression through activating AR signaling." (PMID 34795264, 2021). "We analyzed three PCa data sets and consistently observed that G3BP1 expression directly correlated with AR signaling." (PMID 34795264, 2021). "To avoid misinterpretation due to multiple pre-existing genetic alterations, present in PCa cell lines and patient samples, we performed genetic ablation of G3BP1 in primary mPECs (murine prostate epithelial cells)." (PMID 34795264, 2021). "We propose that G3BP1 overexpression defines a PCa patient cohort that exhibits high AR signaling and sensitivity to AR-targeted therapy." (PMID 34795264, 2021). "Overall, these results demonstrated that AR enhances G3BP1 expression to maintain a feed-forward amplification of AR signaling and sensitizes G3BP1high PCa to AR-targeting drugs." (PMID 34795264, 2021). "Conversely, several genes involved in apoptosis were upregulated upon G3BP1-KO, indicating potentially important roles of G3BP1 in PCa." (PMID 34795264, 2021). "Next, we tested whether negative regulation of SPOP ubiquitin ligase activity by G3BP1 would promote migration and invasion of PCa cells." (PMID 34795264, 2021). "Moreover, G3BP1 contributes to stress granule formation to protect mRNAs under adverse conditions; such protection is thought to be involved in PCa tumorigenesis and response to therapy." (PMID 34795264, 2021). "Our study supports a fundamental role of G3BP1 in disabling the tumor suppressive Cul3SPOP, thus defining a PCa cohort independent of SPOP mutation." (PMID 34795264, 2021). "Future studies should address whether it is the G3BP1-mediated suppression of SPOP or other SPOP-independent G3BP1 functions, such as stress granule formation that facilitates PCa progression to higher grade tumors." (PMID 34795264, 2021). "To assess G3BP1-SPOP signaling in SPOP-mutant PCa, we generated Pten−/−-SPOPF133V mPECs with doxycycline (DOX)-inducible G3BP1 as a model of G3BP1high SPOPF133V PCa." (PMID 34795264, 2021). "Taken together, these findings clearly demonstrated that G3BP1 regulates a molecular program where the SPOP ubiquitin ligase function is compromised, resulting in increased accumulation of SPOP substrates that drive migration and invasion of PCa cells." (PMID 34795264, 2021). "Next, we attempted to determine whether silencing of G3BP1 can reinvigorate the SPOP function, so that SPOP can degrade its substrates that are responsible for PCa progression." (PMID 34795264, 2021). "Notably, there were only a limited number of CRPC cases available in our PCa TMAs as acquiring CRPC samples often requires metastatic biopsy, thus, future study will assess G3BP1 expression in larger cohort of CRPC as prospective collection becomes more standard." (PMID 34795264, 2021). "Given that in PCa the SPOP mutations are hemizygous in nature and G3BP1 binds to wild-type SPOP but not SPOPF133V mutant, our results suggest that G3BP1 adds another layer of negative regulation of remaining SPOPWT allele on top of the existing tumor-promoting effect of SPOPF133V." (PMID 34795264, 2021). "Notably, G3BP1 protein levels were found to be high in PCa tumors featuring either SPOPWT or SPOPMut, indicating that PCa-associated G3BP1 overexpression is independent of SPOP mutation status." (PMID 34795264, 2021).
pemphigus (1 paper, 2025). Pemphigus is a group of rare autoimmune diseases that cause blistering of the skin and mucous membranes (mouth, nose, throat, eyes, and genitals).This conditioncan occur at any age, but often strikes people in middle or older age. "Differential expression analysis was conducted to investigate the expression patterns of the five genes (XBP1, FBXO45, SAT2, AIFM1, and ACSL4) and eight other DEGs associated with ferroptosis (G3BP1, WBP11, TET2, IRF8, FASN, GDPD5, H1-4, and HUWE1) in both the pemphigus and control groups." (PMID 40612574, 2025).
prostate (1 paper, 2021). "Altogether, our findings show the feasibility of exploiting the G3BP1-mediated suppression of SPOP’s ubiquitin ligase function for intervention against prostate tumorigenesis." (PMID 34795264, 2021). "Moreover, AR directly upregulates G3BP1 transcription to further amplify G3BP1-SPOP signaling in a feed-forward manner and potentiates AR signaling and promote prostate tumorigenesis." (PMID 34795264, 2021).
sarcoidosis (1 paper, 2025). Sarcoidosis is a multisystemic disorder of unknown cause characterized by the formation of immune granulomas in involved organs. "Among 19 protein-sarcoidosis associations, strong genetic colocalization evidence was observed for 8 pairs, including BTN3A3, ANXA11, ITPKA, BTN3A1, G3BP1, IL1RN, IL2RB, and NFKB1." (PMID 40075078, 2025).
Sepsis (1 paper, 2023). Sepsis is defined as life-threatening organ dysfunction caused by a dysregulated host response to infection. "To further elucidate the effect of SG activation on myocardial dysfunction in sepsis, we overexpressed G3BP1 to promote SG formation in CMs with a CRISPR-Cas9 plasmid." (PMID 37312024, 2023).
skin cutaneous melanoma (1 paper, 2025). "To further validate this observation, we analyzed data from the GEPIA dataset, which revealed significantly elevated G3BP1 expression in skin cutaneous melanoma (SKCM) samples compared to non-tumor tissues." (PMID 41148289, 2025).
small intestinal NETs (1 paper, 2014). "Because miR-129-5p targets both G3BP1 and EGR1 we propose, that miR-129-5p is an important regulator of oncogenic signals in small intestinal NETs." (PMID 25546138, 2014).
steatosis (1 paper, 2023). Increased lipid within the cytoplasm of cells. "Mice lacking G3BP1 in hepatocytes had more severe steatosis and a more aggravated steatohepatitis phenotype than control mice, further validating that hepatocyte SGs protected mice from steatohepatitis." (PMID 38090607, 2023).
tauopathy (1 paper, 2019). Neurodegenerative disorders involving deposition of abnormal tau protein isoforms (tau proteins) in neurons and glial cells in the brain. "Many of the RBPs associated with the spliceosome aggregate in AD and mouse models of tauopathy, some co-localizing with tau inclusions, such as TIA1, and others forming independent inclusions, such as TDP-43, U1–70K, and G3BP1." (PMID 31875547, 2019).
urinary system tumors (1 paper, 2025). "In recent years, numerous studies have demonstrated the association of G3BP1 with various diseases, such as digestive system tumors, reproductive system tumors, urinary system tumors, and respiratory system tumors." (PMID 40762925, 2025).
infection (108 papers, 2011 to 2026). The state of being infected such as from the introduction of a foreign agent such as serum, vaccine, antigenic substance or organism. "When G3BP1 predominantly interacts with its native SG-associated partners during the early stages of infection, G3BP1 serves an antiviral role by triggering SG formation." (PMID 38492217, 2024). "In contrast, the replication of both SeV and VSV increased in G3BP1-deficient cells compared with wild-type cells at all examined time points post-infection." (PMID 31827077, 2019). "Expression of mutated cleavage-resistant G3BP1 in cells can preserve or restore SG formation during infection." (PMID 27043612, 2016). "From these observations, we conclude that the interaction of SFV nsP3 with the NTF2-like domain of G3BP1 is required for efficient formation of viral replication complexes early in infection and is associated with the appearance of increased numbers of CPVs, often found in clusters." (PMID 31199850, 2019). "We first examined whether G3BP1-positive granular structures were formed during infections by a series of C knocked-out and mutated SeV recombinants and the parental Z strain by immunofluorescence microscopy." (PMID 26300870, 2015). "During the early stages of infection, the viral factory is surrounded by the rough endoplasmic reticulum, which attracts essential translation initiation factors, including G3BP1 and Caprin-1." (PMID 40733530, 2025). "Since IE180 protein is the only immediate early protein of PRV, PRV IE180 protein was detected to facilitate the observation of infected cells throughout the infection, and G3BP1 was detected as a marker to evaluate SG formation via immunofluorescence assays." (PMID 40145738, 2025). "As observed with Ab #1, the intensity of the ~65 kDa G3BP1 band decreased, while the intensity of the ~58 kDa G3BP1 band increased with time after infection." (PMID 40548742, 2025). "Strikingly, we observed fulminant SG formation, despite substantial G3BP1 cleavage during CVB3–2Amut infection." (PMID 40875754, 2025). "For example, porcine epidemic diarrhea virus (PEDV) triggers the induction of SGs early in infection but triggers cleavage of G3BP1 via caspase 8 to inhibit their formation late in infection." (PMID 40145738, 2025). "Enterovirus 71 (EV71) employs its 3C protease to cleave G3BP1 during late infection, dismantling SG to enhance viral replication." (PMID 40731944, 2025). "In Chikungunya virus (CHIKV) infection, nsP3 recruits G3BP1 to viral replication complexes via its C-terminal FGDF motif binding to the NTF2-like domain of G3BP1, blocking SG assembly and enhancing viral RNA translation." (PMID 40731944, 2025). "During murine norovirus (MNV) infection, G3BP1 is redirected to viral replication complexes, preventing SG nucleation." (PMID 40731944, 2025). "In the cytoplasm of SHFV-infected cells, G3BP1 localized to the same regions as the viral dsRNA throughout the course of the infection." (PMID 40548742, 2025). "It was shown that circHOMER1 can, indeed, bind to G3BP1 and that this association was enhanced after VSV-GFP infection." (PMID 40662732, 2025). "For example, the HIV Gag protein interacts with G3BP1 to suppress the formation of SGs, thereby establishing productive infection." (PMID 40733530, 2025). "MA104 cells were mock-infected or infected with SHFV at an MOI of 0.1, and cell lysates were harvested at different times after infection for WB analysis using G3BP1 Ab #1." (PMID 40548742, 2025). "The infection of PK-15 cells with the PCV2 virus (MOI = 1) significantly enhanced the expression of G3BP1 mRNA and protein at 12 and 24 h post-infection." (PMID 39940851, 2025). "The observation that only some cells expressing G3BP1-F124W produced VARCs during infections suggested individual cell variations can affect condensation of the viral gRNAs." (PMID 38295168, 2024).
infection (continued). "Overexpression of G3BP1 inhibited BPIV3 replication, while reducing G3BP1 expression promoted BPIV3 replication, suggesting that G3BP1 plays an important role in BPIV3 infection." (PMID 38690262, 2024). "Short-term infection with porcine epidemic diarrhea virus stimulates the assembly of stress granules, followed by viral activation of caspase 8 that cleaves G3BP1 and depolymerizes SGs." (PMID 38690262, 2024). "Virion-associated fraction were then challenged in A549-ACE2 cells in a second round of infection, and a 3.6-fold decrease in viral titer (TCID50/mL) was observed in the virion-associated fraction of G3BP1/2 KD cells compared to the control." (PMID 38245532, 2024). "As predicted, infection with SARS-CoV-2 F17A led to persistent G3BP1 condensates even during late stages of infection, when the N protein was highly expressed and cells began to exhibit syncytium morphology, suggesting an inability to disassemble SGs." (PMID 38492217, 2024). "To better delineate the function of these factors in viral replication, we further examined the impact of G3BP1/2 downregulation in a single round of infection." (PMID 38245532, 2024). "Conversely, when primarily interacting with the viral N protein, which is more prevalent during the later stages of infection, G3BP1 assumes a pro-viral role by assisting the N protein in viral replication processes." (PMID 38492217, 2024). "Compared with control dimethyl sulfoxide (DMSO), CHX treatment caused the dispersion of G3BP1-positive granules in JS2008-infected cells, supporting the authenticity of the SGs induced by JS2008 infection." (PMID 39445805, 2024). "As expected, N-RATA did not colocalize with G3BP1 but did accumulate with dsRNA, demonstrating that SARS-CoV-2 N recruits G3BP1 to RTC early in infection." (PMID 39638802, 2024). "During BPIV3 infection, downregulation of G3BP1 transcription and translation was a notable finding." (PMID 38690262, 2024). "Next, we compared the spatial distribution of N and S proteins in control and G3BP1/2 KD cells after a single round of infection (at 10 hpi)." (PMID 38245532, 2024). "In summary, these results revealed that G3BP1 plays a role in recruiting the translation machinery to viral factories for the production of nascent viral mRNA at early times post infection." (PMID 39638802, 2024). "As expected after several rounds of infection, depletion of G3BP1/2 dampened SARS-CoV-2 replication, leading to the decrease of N and S levels in total cell lysate as compared to control (Total cell lysate)." (PMID 38245532, 2024). "G3BP1 also assembles SGs in response to infection-mediated translation arrest and limits the availability of translation factors for viral protein synthesis." (PMID 36851663, 2023). "Given that G3BP1 is also modified by phosphorylation and ubiquitylation, it is worth checking the status of G3BP1 for other post-translation modification at different infection stages and determine how these modifications affect a viral life cycle." (PMID 36851663, 2023). "MNV remodels G3BP1 interactome in infected cells and induces cytoplasmic G3BP1 granules during infection that are distinct from SGs." (PMID 36851663, 2023). "To determine if G3BP1 had any direct impact on viral replication, we monitored levels of viral mRNA during a time course infection in G3BP1 KD cells and compared to WT RTgill cells." (PMID 36851680, 2023). "Infection with the mutant virus results in delayed SG disassembly and reduced viral structural protein synthesis in neuronal cells, suggesting that G3BP1 ADP-ribosylation regulates virus production." (PMID 36851663, 2023). "Here, we explore the mechanisms by which different viruses regulate G3BP1 function during infection." (PMID 36851663, 2023). "Taken together, these results further demonstrate that G3BP1 suppresses antiviral signaling during VHSV Ia infection." (PMID 36851680, 2023).